LEP (leptin)
Diseases named in the same sentence as LEP in open-access papers (continued):
Sharing a sentence is not in itself a finding about the gene and the disease.
Insulin resistance (continued). "Moreover, Tregs expressing the TGF-β-dependent latency-associated peptide reduce insulin resistance in leptin-deficient ob/ob mice." (PMID 31297120, 2019). "LEP is an adipokine that regulates food intake by suppression of appetite, and high LEP levels in serum are associated with inflammation, oxidative stress, and the development of CD and insulin resistance." (PMID 30764545, 2019). "Leptin is independently associated with insulin resistance and is angiogenic, which may help explain why breast cancer survivors with excess weight have negative breast cancer outcomes." (PMID 29587682, 2018). "This leptin-based attenuation of the diurnal variations in sweet taste recognition thresholds may also be indirectly linked with the development of insulin resistance in OW/Ob subjects." (PMID 29498693, 2018). "However, in these OW/Ob individuals, the magnitudes of the diurnal variation for plasma leptin and sweet taste recognition thresholds were negatively associated with insulin resistance HOMA-IR scores." (PMID 29498693, 2018). "Humans with single nucleotide polymorphisms in the MC4R are morbidly obese, hyperphagic, and have elevated leptin levels and insulin resistance; those with deficiencies in the leptin or leptin receptor gene, or BDNF-related genetic polymorphisms also have hyperphagic obesity." (PMID 29867590, 2018). "However, the evidence surrounding the effects of chickpea and soybean isoflavones on leptin levels, and the association with insulin resistance, is inconclusive at this time and requires further investigation." (PMID 29601521, 2018). "Higher overall adiposity levels are associated with increased IL-6, TNF-α, and leptin expression, and lower adiponectin expression, which all could promote an insulin resistance state." (PMID 29867770, 2018). "A leptin resistance with increased leptin levels in blood and decreased sensitivity to leptin in the hypothalamus in the obese individuals has been proposed, which may also confer the association of leptin with insulin resistance parameters." (PMID 28542631, 2017). "Therefore, it seems paradoxical that a positive association between low serum leptin levels and insulin resistance was found in cancer patients." (PMID 28830524, 2017). "Furthermore, we aimed to compare the immunoreactive and bioactive leptin levels associations with parameters of insulin resistance and insulin secretion in obese children and adolescents." (PMID 28542631, 2017). "In this context, from a methodologic point of view, we have several concerns including unmatched body mass index (BMI) values of study participants, and the presence of a probable insulin resistance (IR), which is associated with preterm birth and serum leptin levels." (PMID 28890432, 2017). "In addition, HFD increased circulating leptin and adiponectin in both females and males, but the L/A ratio, a reliable marker of metabolic risk that has been also related to insulin resistance, was significantly increased by PNS only in males." (PMID 28706476, 2017). "Also, there was a significant association between insulin resistance and serum leptin concentrations." (PMID 29021828, 2017). "Protein restriction during gestation and/or lactation also resulted in unfavorable intergenerational effects on biometric parameters (i.e., body mass and fat mass) and on glucose, insulin, and leptin metabolism, thereby causing insulin resistance in F1 and F2 adult rat progeny." (PMID 28750655, 2017). "Leptin is a hormone produced by adipose tissue which is implicated in insulin resistance, and may play a role in the etiology of T2DM." (PMID 29021828, 2017). "Furthermore, higher waist circumference, leptin and insulin resistance have been significantly linked with higher oxLDL levels in pediatric populations." (PMID 29077566, 2017). "Furthermore, the association of hot flash-insulin resistance was attenuated by leptin and adiponectin." (PMID 28448547, 2017).
Insulin resistance (continued). "Interestingly, the association of leptin with body adiposity persisted after additional adjustment for insulin resistance index." (PMID 27598982, 2016). "It is known that insulin resistance is present in cirrhosis caused by hepatitis C virus - uncommon in other viral hepatitis - and this resistance would consequently have to explain the high levels of leptin." (PMID 28076486, 2016). "Increased blood pressure related to increased WC, WHR or WSR could be explained by the increase in visceral fat that is associated with the increase in leptin and insulin resistance and worse lipid profiles." (PMID 26934390, 2016). "Insulin resistance (characterized by higher serum insulin levels) is strongly linked to abdominal and visceral obesity, and adipose tissue is known to release adipokines, including leptin and adiponectin, into the systemic circulation." (PMID 27242922, 2016). "Indeed it has been shown that specifically restoring hypothalamic leptin action in leptin receptor deficient rats improved whole body insulin resistance by enhancing hepatic insulin sensitivity." (PMID 27273128, 2016). "Pharmacologic or genetic induction of ER stress in the hypothalamus caused central leptin and insulin resistance, resulting in increased food intake, glucose intolerance, and hypertension, whereas reduction of ER stress significantly alleviated these metabolic derangements." (PMID 26610463, 2015). "Many studies have indicated the association between insulin resistance and serum leptin levels." (PMID 26550014, 2015). "Therefore, deficiency of leptin or its receptors facilitates obesity, increases insulin resistance and impairs glucose tolerance." (PMID 26379757, 2015). "Furthermore, leptin is a circulating hormone produced by adipocytes and is associated with insulin resistance in patients with PCOS." (PMID 26473366, 2015). "Additionally, visceral fat secretes hormone like components, such as free fatty acids and adipokines, like leptin, causing insulin resistance, and all are able to increase sympathetic activity." (PMID 26394362, 2015). "Furthermore, inflammatory cytokine levels, including high TNF-α, high leptin levels, and low adiponectin levels, are associated with insulin resistance in obese children and also affect physical activity during the growth and maturation process." (PMID 26011530, 2015). "Furthermore, leptin has been demonstrated to be associated with the development of insulin resistance and diabetes." (PMID 26473366, 2015). "On the other hand, there are evidences that increased hunger hormone (ghrelin) levels, decreased leptin levels, and increased systemic inflammatory response are linked to insulin resistance and are suggested underlying pathophysiology in the developments of prediabetes." (PMID 26351585, 2015). "It is possible that ADPN and LEP may be the risk markers for fat-induced dyslipidemia or insulin resistance, with a risk for type 2 diabetes and cardiovascular disease." (PMID 26389928, 2015). "It was demonstrated that insulin resistance is associated with elevated plasma leptin levels." (PMID 26578976, 2015). "Although the correlation between plasma leptin levels and LV wall thickness might be driven by insulin resistance, leptin remained independently associated with LV wall thickness in the multivariate model even after adjusting for insulin action." (PMID 26064110, 2015). "Interestingly, insulin resistance is associated with decreased levels of adiponectin and increased levels of leptin, reflecting a state of adiponectin deficiency and leptin resistance." (PMID 25838947, 2015). "Inflamed and abnormally differentiated adipocytes are, on the other hand, a source for pro-inflammatory cytokines (e.g. TNFα, interlukin-8) and adipokine (e.g. leptin) which predispose to atherosclerosis and further aggravation of insulin resistance and diabetes." (PMID 25714093, 2015).
Insulin resistance (continued). "In the overall sample, the linear regressions exploring the associations of ghrelin, adiponectin and leptin with age, gender, BMI z-score, HOMA-IR and tanner stage as independent variables showed strong associations of leptin levels with weight status and insulin resistance at baseline." (PMID 26581745, 2015). "To address whether Ago2 mediates the compensatory expansion of β cells during insulin resistance, we next crossed mice carrying the Ago2-floxed allele onto the ob/ob background to generate mice deficient in both Ago2 and leptin (Ago2ob)." (PMID 24361012, 2014). "Interestingly, miR-184 is unique as the most downregulated islet miRNA during insulin resistance, and additionally, administration of the ketogenic diet in leptin-deficient ob/ob mice rescued its expression." (PMID 24361012, 2014). "Moreover, previous study indicated that increased leptin was positively associated with hyperinsulinemia and insulin resistance." (PMID 23590862, 2013). "MSG may cause obesity and nonfatty liver and increased mRNA level of IL-6, TNFα, resistin, and leptin in visceral fat tissue, which might all predispose insulin resistance in later life." (PMID 24455747, 2013). "Furthermore, leptin interferes with insulin signaling, and plasma levels of leptin directly correlate with the degree of insulin resistance in patients with T2D, whose association with breast carcinoma has been well studied." (PMID 23819063, 2013). "Two adipokines, leptin and adiponectin, may be risk markers of fat-induced dyslipidemia and insulin resistance." (PMID 23533722, 2013). "Three leptin-deficient adults with a missense mutation of the leptin gene were evaluated during treatment with recombinant methionyl human leptin (r-metHuLeptin), and the therapy was found decrease insulin resistance." (PMID 23579596, 2013). "Similarly, association between serum leptin, insulin resistance, and metabolic syndrome was mediated through central obesity in a cross-sectional study on Iranian population." (PMID 24455217, 2013). "Although the precise cause remains unclear, insulin resistance, inflammation, and elevated circulating levels of ghrelin and leptin have been implicated in this process." (PMID 23809614, 2013). "This may lead to functional resistance to insulin and leptin, which may underlie permanently an increase in food intake, overweight, and insulin resistance." (PMID 24455747, 2013). "Further, leptin level was associated with insulin resistance and all other components of MetS." (PMID 23514611, 2013). "Leptin might be a marker of risk of coronary artery disease, at least in men, and contributes to the risk profile in subjects with insulin resistance." (PMID 22642879, 2012). "Interestingly, leptin was found to be directly associated with appetite and insulin resistance, suggesting that these patients are resistant to the orexigenic effects of hypoleptinemia." (PMID 22518191, 2012). "Insulin resistance in obese individuals may also be associated with high levels of plasma leptin and low levels of adiponectin." (PMID 22899917, 2012). "Leptin is also associated with increased insulin resistance, which can cause hyperlipidemia." (PMID 22027268, 2011). "Associations between insulin resistance and leptin levels have been reported in children." (PMID 21904547, 2011). "The aim of this study was to investigate sex differences and associations of high molecular weight (HMW) adiponectin, leptin and proinflammatory adipokines, individually or in combinations, with adiposity and insulin resistance (IR) measures in prepubertal childhood." (PMID 21365005, 2011). "In summary, female sex was associated with higher levels of inflammatory markers, insulin-resistance promoting adipokines (leptin and resistin), natriuretic peptides, markers of calcification and coagulation factor levels and activity, potentially contributing to higher CVD risk." (PMID 20140090, 2010).
Insulin resistance (continued). "Thus, for example, lipoatrophy-associated insulin resistance can be completely reversed by the combination of adiponectin and leptin, but only partially by either adiponectin or leptin alone." (PMID 20180981, 2010). "Thus, insulin resistance is likely to be associated with regulation of leptin metabolism in smokers." (PMID 19736607, 2009). "However, leptin concentration was associated with HOMA values and higher leptin concentration was found among adolescents with insulin resistance." (PMID 18553029, 2008). "We hypothesized that children with metabolic syndrome and SDB have increased SNSA, leptin levels, and insulin resistance and that treating SDB will be associated with improvement in metabolic derangements." (PMID 18762497, 2008). "Therefore, it would appear that low leptin concentrations, increased fat oxidation and insulin resistance are associated with increased concentrations of cortisol and interleukin-6 in weight-losing patients with pancreatic cancer." (PMID 15026790, 2004). "Moreover, high BMI was associated with the secretion of leptin and adiponectin, which could result in insulin resistance and activation of the downstream pathways, contributing to cancer development." (PMID 40777176, 2025). "Competitive binding of E3 and E2 to the estrogen receptor and decreased expression of both estrogen receptors in cases of GDM, which coincides with increased leptin expression and the associated increase in pro-inflammatory cytokines may contribute to the development of insulin resistance." (PMID 40235646, 2025). "-High association with WAT mass and leptin in women.-Lower association with BMI, WAT mass and leptin in men.-Weight loss increases T in older men, and decreases T in older women.-Protective against T2D in men.-Inversely correlated with insulin resistance in men." (PMID 41180177, 2025). "HFD‐induced insulin resistance may be associated with mitochondrial DNA damage, oxidative stress, adipose tissue inflammation, and impaired hypothalamic and leptin transduction pathways." (PMID 41292674, 2025). "Third, previous studies demonstrated that VAT-induced adiponectin and leptin were significantly associated with insulin resistance, which could affect kidney functions, increase reabsorption of uric acid, decrease excretion of uric acid, and lead to hyperuricemia." (PMID 38405154, 2024). "Metformin promotes weight loss through improving insulin resistance, decreasing gastrointestinal absorption of carbohydrates, it also has lipolytic and anorectic effect through its ability to modify the appetite regulatory centers in the hypothalamus and it can decrease leptin levels." (PMID 38869746, 2024). "Moreover, this biomarker correlates better with insulin resistance than adiponectin or leptin alone, and its reduction is associated with an increase in the number of metabolic changes and has thus been proposed to be an important predictive marker for metabolic syndrome." (PMID 38063544, 2023). "However, other studies on survival confirmed that visceral fat is not related to survival, and the more subcutaneous adipose tissue that produces leptin, the more number of patients who can be protected from insulin resistance, which causes cachexia, tumor progression, and metastasis." (PMID 36835962, 2023). "High levels of LEP (leptin) associated with increased MBL in RA with PD patients further enforce previous findings of increased LEP levels found in dysfunctional immune phenotype including insulin resistance, inflammation, and disturbances in hemostatic factors." (PMID 35327515, 2022). "Therefore, we wished to determine whether leptin levels could be an independent risk factor for predicting insulin resistance." (PMID 36143007, 2022).
Insulin resistance (continued). "Leptin and resistin are proinflammatory adipokines associated with energy homeostasis, the central control of food intake, inflammation, cardiovascular disease, and insulin resistance, while adiponectin has antidiabetic, anti-inflammatory, and antiatherogenic properties." (PMID 36500974, 2022). "Furthermore, serum leptin levels may be an independent risk factor for insulin resistance according to our study." (PMID 36143007, 2022). "In pregnancy, the placental production of leptin represents the major sources of higher levels of maternal circulating leptin and contributes to maternal fat mass gain which could further aggravate the insulin resistance associated with pregnancy and the onset of GDM." (PMID 35566560, 2022). "Besides, high BMI is associated with higher insulin resistance and leptin production, both of which could significantly impact the UA secretion system, resulting in an elevated level of UA." (PMID 36188459, 2022). "Besides, diet and exercise interventions implemented in overweight/obese BC survivors may improve metabolic risk, insulin resistance and leptin biomarkers." (PMID 34350120, 2021). "Because leptin synergistically acts with insulin to induce its anorexigenic actions, and considering that hypothalamic insulin resistance has been show to underlie deregulation in food intake, we wondered whether insulin signaling in the hypothalamus may be affected after a short-term HFD feeding." (PMID 34015524, 2021). "However, pregnancy is associated with leptin insensitivity which suppresses the action of leptin and may even promote insulin resistance and impairment of glucose tolerance." (PMID 34884524, 2021). "In our study, no weight reduction was found, but a marked decrease in fat mass, which may explain the reduction in leptin and the increase in adiponectin compared to the control group at the end of the exercise protocol, reducing the risk of inflammation and insulin resistance." (PMID 34746212, 2021). "In addition to the positive associations of IL-6 and leptin with insulin resistance and secretion, NGF was higher in the GDM patients and strongly linked to glucose metabolism, insulin resistance and pancreatic β cell function in Chinese pregnant women in the second trimester." (PMID 33292292, 2020). "Similarly, we found that baseline IL-6 and leptin levels were higher in participants with glycemic progression at the 10-year follow-up and that leptin level was significantly associated with higher glucose level, insulin resistance, and dyslipidemia." (PMID 31690939, 2020). "Therefore, in GDM, associated with insulin resistance, hyperinsulinemia and hyperleptinemia, flavonoids might downregulate the synergistic interaction between insulin and leptin signaling in the inflammatory processes." (PMID 32630697, 2020). "Similarly, a study using leptin-deficient ob/ob mice showed that specific ablation of the Nrf2 gene in adipocytes led to reduced white adipose tissue mass, but resulted in more severe metabolic syndrome with aggravated insulin resistance." (PMID 32971975, 2020). "In addition, plasma levels of leptin correlate with BMI and high leptin levels may exacerbate insulin resistance, thus predisposing individuals to miscarriage." (PMID 31823750, 2019). "On the one hand, this effect is related to the slightly reduced food intake, which may be partially associated with the lowered serum leptin induced by 3 mg/kg LH-21 because elevated plasma leptin is correlated with hyperphagia, insulin resistance, and other constituents of metabolic syndrome." (PMID 29731737, 2018). "Sleep deprivation may be deleterious with respect to DR as it has been associated with increased ghrelin and leptin levels (which increases hunger and decreases satiety, and tilts the energy balance towards excess), as well as insulin resistance and poorer glycemic control." (PMID 29795569, 2018).